INHBA (inhibin subunit beta A)
Diseases named in the same sentence as INHBA in open-access papers (continued):
Sharing a sentence is not in itself a finding about the gene and the disease.
keloid (2 papers, 2010 to 2020). An irregularly shaped, elevated mark on the skin caused by deposits of excessive amounts of collagen during wound healing. "INHBA gene is the regulator of G-protein signaling 4 and shown to be differentially altered in fibroblasts isolated from spatially distinct areas of the keloid." (PMID 32085797, 2020). "The authors observed an increased mRNA expression of INHBA in fibroblasts derived from all lesional sites of keloids when compared with external control skin." (PMID 20418938, 2010). "Previously INHBA has been suggested to be a possible target gene by Seifert et al7 in a microarray study performed on fibroblasts derived from keloids and external control skin." (PMID 20418938, 2010). "INHBA showed a significant 14-fold upregulation in keloid margin samples (P = .031)." (PMID 20418938, 2010). "A statistically significant (P < .05) differential expression and a fold change of more than 2 were determined between keloid margin and internal control biopsy samples for 10 genes, including ACAN, ASPN, C5orf13, HIF1A, IGFBP7, INHBA, LGALS1, PTN, SERPINH1, and TNFAIP6." (PMID 20418938, 2010).
kidney cancer (2 papers, 2014 to 2022). Primary or metastatic malignant neoplasm involving the kidney. "We used quantitative RT‐PCR to measure the levels of three TGF‐beta pathway components (TGFB2, INHBA, and SMAD3) and two TGF‐beta targets (THBS1 and CDKN2B) which were previously found to be significantly lower in FLCN‐deficient kidney cancer cells and tumors." (PMID 25121506, 2014).
mesothelioma (2 papers, 2017 to 2024). A usually malignant and aggressive neoplasm of the mesothelium which is often associated with exposure to asbestos. "Notably, ADAM metallopeptidase domain 10 (Adam10) and inhibin subunit beta A (Inhba) were also upregulated, and their upregulation was predicted to lead to the activation of mesothelioma formation." (PMID 38297314, 2024). "Therefore, we analyzed the mRNA expression levels of INHBA (activin-A subunit), TGFB1 and TGFB2 in mesothelioma cells." (PMID 29228689, 2017).
neuroblastoma (2 papers, 2006 to 2011). Neuroblastoma (NB) is the most common solid, extracranial childhood tumor. "A high expression of INHBA was associated with a favourable prognostic outcome, exerting a tumour suppressor and anti-angiogenic role in neuroblastoma patients." (PMID 21897392, 2011).
non-small cell lung carcinoma (2 papers, 2019 to 2021). A group of at least three distinct histological types of lung cancer, including non-small cell squamous cell carcinoma, adenocarcinoma, and large cell carcinoma. "In non-small-cell lung cancer, INHBA has been shown to induce and maintain mesenchymal phenotypes of cancer stem-like cells and to promote cancer cell metastasis." (PMID 31827640, 2019).
Obesity (2 papers, 2020 to 2024). Accumulation of substantial excess body fat. "From a biomarker perspective we have also identified several genes elevated in IMF that encode proteins that have been connected to human obesity and potentially could be detectable in the plasma; these include INHBA and ANGPTL7." (PMID 31992204, 2020).
Oral carcinoma (2 papers, 2015 to 2020). "The result supports the assumption that, in vitro, INHBA influences LIF-associated metastasis in oral cancer." (PMID 31973037, 2020). "To validate our findings, we determined the correlation between LIF and INHBA mRNA expression in patients with oral cancer by quantitative real-time PCR." (PMID 31973037, 2020). "Oral carcinoma cells in culture expressed activin A and knock down with specific siRNA against INHBA reduced growth and induced invasion of tumor cells." (PMID 26317418, 2015).
pancreatic ductal adenocarcinoma (2 papers, 2022 to 2024). An infiltrating adenocarcinoma that arises from the epithelial cells of the pancreas. "In addition, INHBA expression was associated with a Myo-CAF profile in pancreatic ductal adenocarcinomas." (PMID 36009475, 2022).
urothelial carcinoma (2 papers, 2019 to 2022). A malignant neoplasm derived from the transitional epithelium of the urinary tract (urinary bladder, ureter, urethra, or renal pelvis). "According to several studies, the overexpression of INHBA is associated with lung, esophageal, colon, gastric, prostate, and urothelial carcinoma." (PMID 35216189, 2022). "We opted to further investigate the role of INHBA in urothelial carcinoma based on the discovery of hypomethylation and the high expression of the INHBA gene in UTUC." (PMID 35216189, 2022). "INHBA was detected by real-time PCR and immunohistochemistry staining, and was found to be highly expressed in clinical tissues and cell lines of urothelial carcinoma." (PMID 35216189, 2022). "INHBA may affect urothelial carcinoma migration by reorganizing the extracellular matrix through the SMAD pathway." (PMID 35216189, 2022). "Therefore, we opted to further dissect the correlation between the expression of INHBA and the genes that affect aggressive behavior in urothelial carcinoma." (PMID 35216189, 2022). "Our in vitro study showed that the aggressive behavior of urothelial carcinoma could be reversed by INHBA downregulation based on cell viability and migration assays." (PMID 35216189, 2022). "Real-time PCR analyses of the high-grade urothelial carcinoma cell lines (T24 and BFTC-909) revealed higher INHBA expression levels than low-grade urothelial carcinoma cell lines (RT4 and UM-UC-14)." (PMID 35216189, 2022).
ameloblastoma (1 paper, 2020). The most common odontogenic tumor, arising from the epithelial component of the embryonic tooth and usually affecting the molar-ramus region of the mandible or maxilla. "Accordingly, western blot analysis showed that protein expression levels of IGF‐II, TLR2, and INHBA were significantly increased in the ameloblastoma tumors compared to normal tissues." (PMID 32096304, 2020). "Moreover, our qRT‐PCR analysis, as well as microarray data, showed that mRNA expression levels of INHBA, IGF2, and TLR2, all of which are classified into the KRAS‐responsive gene sets, significantly increase in ameloblastoma compared to normal counterpart tissues." (PMID 32096304, 2020).
brain injury (1 paper, 2018). Acute and chronic (see also brain INJURIES, CHRONIC) injuries to the brain, including the cerebral hemispheres, CEREBELLUM, and brain STEM. "We observed increased densities of cells positive for the activin-A subunit INHBA in the brain parenchyma in injured vs. non-injured areas, consistent with previously reported elevated INHBA in the cerebrospinal fluid following perinatal brain injury." (PMID 29397421, 2018).
Cachexia (1 paper, 2020). Severe weight loss, wasting of muscle, loss of appetite, and general debility related to a chronic disease. "Here we observed positive association of INHBA with CWLG (r = 0.50, p = 0.0077), and negative association of WFIKKN (r = −0.52, p = 0.0068, consistent with increased Activin activity as a mechanism of cachexia." (PMID 33334063, 2020).
cardiomyopathies (1 paper, 2022). "Our data suggested similar dysregulation of these molecular pathways in adult-onset cardiomyopathies with increased BMP6 and NRG1 in EC7 and decreased INHBA." (PMID 35926050, 2022).
cholesteatoma (1 paper, 2023). A pathologic process characterized by the proliferation of keratinizing squamous epithelium resulting in the accumulation of keratin and cells in the middle ear and/or mastoid. "Subcluster 8 was composed of the most differentiated cholesteatoma-specific fibroblasts and exhibited markedly higher INHBA expression levels than the other subclusters in the cholesteatoma-specific fibroblasts." (PMID 37537159, 2023). "The expression of INHBA was significantly upregulated in fibroblasts from a mouse model of cholesteatoma compared to controls." (PMID 37537159, 2023). "We also confirmed INHBA expression at the mRNA level in the cholesteatoma fibroblasts using droplet digital polymerase chain reaction (ddPCR)." (PMID 37537159, 2023). "Here, we demonstrated that the INHBA antagonist FST reduced ectopic osteoclastogenesis in a cholesteatoma mouse model." (PMID 37537159, 2023). "This study identified a subset of osteoclastogenic fibroblasts expressing INHBA/activin A in human cholesteatoma." (PMID 37537159, 2023). "We visualized INHBA expression levels across all clusters in UMAP and confirmed that INHBA was highly expressed in cluster 5, the cholesteatoma-specific fibroblast subset, although INHBA expression was also seen in endothelial cells, albeit at low levels." (PMID 37537159, 2023). "Next, we examined INHBA expression in cholesteatoma fibroblasts by immunostaining of cholesteatoma sections with anti-INHBA antibodies." (PMID 37537159, 2023). "Cholesteatoma sections exhibited colocalization of INHBA and vimentin, a marker for fibroblasts, indicating that INHBA was present at the protein level in the cholesteatoma fibroblasts." (PMID 37537159, 2023). "The expression of INHBA mRNA normalized relative to glyceraldehyde-3-phosphate dehydrogenase (GAPDH) mRNA was significantly higher in cholesteatoma fibroblasts than in control dermal fibroblasts." (PMID 37537159, 2023). "Additionally, universal fibroblast marker gene PI16 mRNA expression was decreased by proinflammatory cytokines, suggesting that inflammatory cytokines cause differentiation from human skin fibroblasts with general characteristics to cholesteatoma-specific fibroblasts expressing high levels of INHBA." (PMID 37537159, 2023). "Taken together, these observations indicated that cholesteatoma fibroblasts expressed INHBA at significantly higher levels than control dermal fibroblasts; they suggested that INHBA has potential as a marker gene to identify the more differentiated cholesteatoma-specific fibroblast subset." (PMID 37537159, 2023). "The results showed that INHBA was significantly upregulated relative to INHBB and INHA in cholesteatoma fibroblasts." (PMID 37537159, 2023). "To elucidate the expression of INHBA, INHBB, and INHA in cholesteatoma mouse model fibroblasts, we collected fibroblasts from the cholesteatoma mouse model and control mouse ear pinnae via cell sorting." (PMID 37537159, 2023). "Therefore, we compared the expression patterns of INHBA, INHBB, and INHA in human cholesteatoma fibroblasts by ddPCR." (PMID 37537159, 2023).
colorectal tumors (1 paper, 2025). "Recent research indicates that the INHBA is over-expressed in various cancers and is associated with cell proliferation and outcomes in lung, gastric, esophageal, and colorectal tumors." (PMID 40426863, 2025).
dental caries (1 paper, 2018). The decay of a tooth, in which it becomes softened, discolored, and/or porous. "Both INHBA and INHBA-AS1 were previously associated with dental caries in genome-wide association studies, and INHBA was postulated to play a role in early tooth development." (PMID 29456864, 2018).
diffuse large B-cell lymphoma (1 paper, 2022). "In contrast, INHBA was significantly downregulated and functioned as a tumor suppressor in diffuse large B-cell lymphoma." (PMID 36304286, 2022).
endometrial cancer (1 paper, 2023). Primary or metastatic malignant neoplasm involving the endometrium (mucous membrane that lines the endometrial cavity). "employed transcriptome sequencing technology to analyze 5 pairs of endometrial cancer tissues and normal endometrial tissues, revealing downregulation of ID1, IGF1, GDF7, SMAD9, TGF-β, and WNT4 expression alongside upregulation of GDF5, INHBA, and ERBB4 in endometrial cancer." (PMID 38239355, 2023).
endometriosis (1 paper, 2025). The growth of functional endometrial tissue in anatomic sites outside the uterine body. "Using machine learning algorithms, five key genes were selected in the endometriosis: BST2, IL4R, INHBA, PTGER2, and MET." (PMID 40405976, 2025).
enophthalmos (1 paper, 2020). "Owls and nightjars have relatively large orbits for visual acuity at night; this might be associated with INHBA, mutations of which result in enophthalmos, a condition in humans in which the orbits are enlarged." (PMID 33160317, 2020).
fibrosis (1 paper, 2013). the formation of excess fibrous connective tissue in an organ or tissue in a reparative or reactive process. "A comparison of FST or INHBA gene expression in fibroblasts between patients who had high levels of fibrosis following IR and those who were non-symptomatic was conducted." (PMID 24204752, 2013).
inflammatory bowel disease (1 paper, 2023). A spectrum of small and large bowel inflammatory diseases of unknown etiology. "On the other hand, INHBA was found to be enriched in the TGF-β signaling pathway and inflammatory bowel disease-related pathways." (PMID 37446311, 2023).
lactic acidosis (1 paper, 2026). Metabolic acidosis characterized by the accumulation of lactate in the body. "Metabolomics revealed that stretch-induced mitochondrial dysfunction in PASMCs caused lactic acidosis via enhancement of PDK1 (pyruvate dehydrogenase kinase 1) and c-MYC, leading to increased INHBA expression." (PMID 41568456, 2026).
laryngeal carcinoma (1 paper, 2021). Carcinoma that arises from the laryngeal epithelium. "Survival analysis suggests that high expression of EGFR and INHBA is significantly associated with poor prognosis for laryngeal cancer." (PMID 34093817, 2021). "Among them, EGFR and INHBA were found to be significantly correlated with laryngeal cancer patient prognosis, HSA2 expression and pRS score." (PMID 34093817, 2021). "This suggests that EGFR and INHBA can serve as prognostic hub genes for laryngeal cancer collectively with pRS genes (CFLAR, DAPK2, TSC2, CAPN10, MBTPS2, PEX14, FADD and ST13)." (PMID 34093817, 2021). "Our study suggests that EGFR and INHBA from fibroblasts may lead to malignant transformation of laryngeal cancer." (PMID 34093817, 2021).
limb ischemia (1 paper, 2023). A ischemia that involves the limb. "Collectively, these studies reinforce that a miR-130b/INHBA/IL-8 signaling axis may figure prominently in increasing blood vessel recovery and tissue repair after limb ischemia." (PMID 37097749, 2023).
liver cancer (1 paper, 2021). An epithelial or non-epithelial malignant neoplasm that arises from the liver. "INHBA and INHBB showed opposing effects however in liver cancer where INHBA (HR = 0.62, p = 0.0086) was a strong positive predictor but INHBB (HR = 1.52, p = 0.025) was a potent negative predictor." (PMID 33819300, 2021).
lymphedema (1 paper, 2021). Excess fluid collection in tissues, causing swelling. "Nevertheless, preadipocytes derived from lymphedema subjects exhibited differential expression of GDF15, the marker of mitochondrial stress, and of KLF4, KLF6, INHBA and ZNF423, i.e. genes implicated in adipogenesis, when compared with cells from healthy women." (PMID 33854130, 2021).
Metastatic cancer (1 paper, 2023). A carcinoma which has spread from the original site of growth to another anatomic site. "Metastatic cancer-1 cells highly expressed mesenchymal markers (e.g., VIM, FN1, and COL1A1), typical of EMT, whereas metastatic cancer-2 cells highly expressed partial EMT (p-EMT) signature genes (e.g., LAMC2, PDPN, and INHBA), indicative of a p-EMT phenotype." (PMID 37853464, 2023).
multiple myeloma (1 paper, 2025). "A previous review suggested that INHBA might serve as a therapeutic marker, and the data in this study provide a further experimental basis for its expanded application in more types of cancer than multiple myeloma." (PMID 41008625, 2025).
myelodysplastic syndrome (1 paper, 2022). A clonal hematopoietic disorder characterized by dysplasia and ineffective hematopoiesis in one or more of the hematopoietic cell lines. "Mesenchymal stromal cells inhibited monocytes through upregulating INHBA in patients with myelodysplastic syndrome." (PMID 36039643, 2022).
myeloid neoplasm (1 paper, 2024). Proliferation of myeloid cells originating from a primitive stem cell. "For instance, in MSCs derived from the myeloid neoplasms, a remarkable number of genes belonging to the TGF superfamily genes, such as TGFB-1, various BMPs, and INHBA as well as genes of the WNT signaling pathway, were differentially expressed." (PMID 38893194, 2024).
Myocardial fibrosis (1 paper, 2025). "Additionally, members of the transforming growth factor-beta (TGF-β) superfamily (INHBA, INHBB, NOG) occupy central positions in the protein interaction network, reflecting the dual role of the TGF-β pathway (regulating myocardial fibrosis and vascular plaque stability) at different disease stages." (PMID 41283645, 2025).
osteoarthritis (1 paper, 2020). A noninflammatory degenerative joint disease occurring chiefly in older persons, characterized by degeneration of the articular cartilage, hypertrophy of bone at the margins and changes in the synovial membrane. "Inhibitors of WNT (DKK3 and FRZB), and antagonists of BMP/TGFβ (CD109, CHRDL2, DCN FMOD, INHBA and THBS1) signalling were decreased or absent in the aged inner region, consistent with the reported upregulation of these pathways in IDD and its closely related condition osteoarthritis." (PMID 33382035, 2020).
osteosarcoma (1 paper, 2023). A usually aggressive malignant bone-forming mesenchymal neoplasm, predominantly affecting adolescents and young adults. "INHBA expression was enhanced in human OS samples compared to adjacent normal tissues, indicating that INHBA was upregulated in osteosarcoma cells." (PMID 37940978, 2023).
periodontitis (1 paper, 2026). An acute or chronic inflammatory process that affects the tissues that surround and support the teeth. "A similar upregulation pattern of INHBA was also confirmed in periodontitis-affected human tissues by scRNA-seq analysis." (PMID 42091891, 2026).
polycystic ovary (1 paper, 2023). "Other studies demonstrated decreased expression of FSHR and CYP11A1 and increased expression of CYP19A1, STAR, HSD3B2 and INHBA in polycystic ovary granulosa cells compared to controls." (PMID 36768772, 2023).
renal carcinoma (1 paper, 2016). A carcinoma arising from the epithelium of the renal parenchyma or the renal pelvis. "Among these genes, INHBA, MT1G and SPINT2 were reported to have tumor suppressive functions in renal cancers." (PMID 26551931, 2016).
renal fibrosis (1 paper, 2022). A final common manifestation of a wide variety of chronic kidney diseases characterized by glomerulosclerosis and tubulointerstitial fibrosis. "Since the importance and novelty of INHBA study in renal fibrosis, we further verified the expression of INHBA in protein levels." (PMID 35439976, 2022). "INHBA activates TGF-β signaling pathway and promotes EMT, however its role in renal fibrosis is current unknown." (PMID 35439976, 2022).
renal tumors (1 paper, 2010). "Notably, several key genes involved in TGF-β signaling, such as TGFB2, INHBA, THBS1 and SMAD3, were down-regulated in FLCN-null and mutant FLCN cells as well as in the BHD-associated renal tumors." (PMID 20573232, 2010). "GREM1, TGFB2, INHBA, THBS1 and SMAD3 RNA expression levels were significantly lower in the BHD renal tumors compared to normal kidney tissue." (PMID 20573232, 2010).
Sepsis (1 paper, 2024). Sepsis is defined as life-threatening organ dysfunction caused by a dysregulated host response to infection. "Among them, the interaction of miR-150-3p with INHBA has been reported to inhibit the proinflammatory polarization of alveolar macrophages in sepsis." (PMID 39006030, 2024).
skin squamous cell carcinoma (1 paper, 2023). A carcinoma arising from the squamous cells of the epidermis. "In keeping with a role in promoting tumor immune evasion, INHBA overexpression in keratinocytes in a transgenic model of skin squamous cell carcinoma has been shown to alter the TME by enriching immunosuppressive macrophages and regulatory T cells at the expense of skin-resident γδ T cells." (PMID 38304252, 2023).